MITF (melanocyte inducing transcription factor)
Diseases named in the same sentence as MITF in open-access papers (continued):
Sharing a sentence is not in itself a finding about the gene and the disease.
vitiligo (continued). "In accordance with these previous reports, in treated vitiligo melanocytes, we found that phosphorylation of ERK induces MITF activation at the protein level." (PMID 36429011, 2022). "In melanocytes by qRT–PCR compared to normal human skin melanocytes (PIG1) and in vitiligo melanocytes (PIG3V), the level of miR-125b-5p was increased, and MITF was decreased." (PMID 36438898, 2022). "Relative expression of melanogenesis-related genes MC1R, MITF, tyrosinase, TRP1, and TRP2 varied with age group, line of chicken, visual acuity, and vitiligo status." (PMID 35547230, 2022). "Another study on melanocyte autophagy found that the expression of MITF, TYR, TYRP1, and TYRP2 proteins decreased in vitiligo patients." (PMID 34107850, 2021). "The involvement of MITF in ISG regulation and hair graying is particularly relevant in light of the increasing number of studies indicating an innate immune component to vitiligo." (PMID 29723194, 2018). "Consistent with the results of bioinformatics analysis, the expression levels of PPAR-γ, EDNRB, and TYR were significantly reduced in human non-segmental vitiligo skin along with the reduction of MITF, a key gene for epidermal melanogenesis." (PMID 38159176, 2024). "Subsequently, the results of immunofluorescence staining showed that the expression levels of PPAR-γ, TYR, and EDNRB were significantly reduced in non-segmental vitiligo patients’ lesions skin along with the number of MITF-labeled melanocytes." (PMID 38159176, 2024). "When PMPP, together with Akt inhibitor IV, was introduced to cells in vitro, tyrosinase activity was inhibited, resulting in a severe decrease in melanin content, suggesting that MITF needs the PI3K pathway and that PMPP is a promising agent for the treatment of vitiligo." (PMID 37371141, 2023). "By direct immunofluorescence, we examined the expression of PPAR-γ and melanogenesis-related genes EDNRB, MITF, and TYR in the skin tissues of non-segmental vitiligo patients (n = 5) and healthy people (n = 5)." (PMID 38159176, 2024). "The results showed that the expression of MITF and TYR was almost absent in non-segmental vitiligo lesions compared to healthy skin." (PMID 38159176, 2024).
clear cell sarcoma (18 papers, 2003 to 2026). A rare malignant neoplasm with melanocytic differentiation characterized by the presence of polygonal or spindle shaped clear cells. "MITF has been implicated as an oncogenic factor in certain sarcomas, particularly clear cell sarcoma (CCS)." (PMID 40343114, 2025). "MITF has been identified as a potential oncogenic driver in specific sarcomas, most notably clear cell sarcoma (CCS)." (PMID 41168571, 2025). "EWSR1-CREB1 activates the melanocyte transcription factor MITF, which in turn activates transcription of c-Met, an oncogenic receptor tyrosine kinase recently shown to be activated in clear cell sarcoma." (PMID 24715928, 2014). "In both CRTC1::TRIM11 and MITF::CREM tumors, clear cell sarcoma poses the most challenging differential diagnosis due to their striking similarities." (PMID 39264472, 2024). "In contrast, similar to EWSR1::ATF1 fusion in clear cell sarcoma, both CRTC1::TRIM11 and MITF::CREM fusions likely lead to MITF overexpression through the induction of the CREB signaling cascade." (PMID 39264472, 2024). "Immunohistochemically, clear cell sarcoma shows a phenotype identical to that of conventional melanoma, characterized by strong expression of S100 protein in 100% of cases and expression of HMB-45, Melan-A, and MiTF in 81–97% of cases." (PMID 40310428, 2025). "The observation that EWSR1::ATF1-positive clear cell sarcomas show consistent melanocytic differentiation and expression of the melanocytic-specific MITF (MITF-M) transcript fueled the idea of the EWSR1::ATF1 fusion protein-mediated transactivation of the MITF promoter." (PMID 39769457, 2024).
Waardenburg syndrome type 2 (18 papers, 2009 to 2024). "The aim of this study was to investigate MITF mutations and the clinical characteristics of WS type 2 (WS2) in four Chinese families." (PMID 34323021, 2021). "The exchange of this amino acid residue for a proline due to a mutation in the MITF gene is the cause of the Waardenburg syndrome type II and reveals the central role displayed by GSK-3β in the regulation of pigmentation." (PMID 32674468, 2020). "Contrary to the small range of USH2A pathogenic variants, MITF pathogenic variants causing Waardenburg syndrome type 2 are diverse and usually private, with only a small number of exceptions." (PMID 29293505, 2018). "In contrast, the phosphorylation of MITF on serine 298, a mutation related to Waardenburg syndrome type 2 (WS2), by glycogen synthase kinase 3 enhances the binding to the tyrosinase promoter." (PMID 26024475, 2015). "Indeed, mutations in the human MITF gene can lead to Waardenburg syndrome type 2 (WS2) and Tietz syndrome which are dominantly inherited syndromes with the disease phenotype of hypopigmentation and hearing loss." (PMID 26703580, 2015). "The GSK3β-mediated phosphorylation at Ser298 increases the binding activity of MITF; of note, this is a feature of the Waardenburg syndrome type II, a rare genetic disease characterized by pigmentation defects." (PMID 33332393, 2020). "The activation of KITLG-KIT signaling pathway leads to the activation of downstream MITF, and defective KITLG has been linked to WS type 2." (PMID 33396879, 2020). "Upstream to MITF, pathogenic variants in KITLG have been found to cause WS type 2." (PMID 33396879, 2020).
albinism (16 papers, 2012 to 2025). A congenital disorder characterized by partial or complete absence of melanin pigment in the eyes, hair, or skin. "Biallelic MITF mutations have been found associated with a rare hearing loss syndrome consisting eye abnormalities and albinism; and a more severe type of WS whose heterozygous parents were affected with classic WS in both cases." (PMID 32728090, 2020). "Complete deficiency of microphthalmia transcription factor (MITF) in Mitfmi-vga9/mi-vga9 mice is associated with microphthalmia, retinal dysplasia, and albinism." (PMID 30590377, 2018). "Molecular genetic diagnosis for most patients started with a next-generation sequencing (NGS) panel targeting genes associated with albinism—TYR, OCA2, MC1R, MITF, SLC45A2, TYRP1, and GPR143—as the initial clinical diagnosis for all patients was albinism." (PMID 39457042, 2024). "Although the candidate gene SLC45A2 is known to be involved in albinism in different species, to date in cattle only mutations in the TYR and MITF genes were reported to be associated with albinism or albinism-like phenotypes." (PMID 28982372, 2017).
PEComas (16 papers, 2014 to 2025). "Additionally, immunohistochemical markers such as CD10+, HMB45-, melan-A-, and melanocyte-inducing transcription factor help to differentiate them from PEComas." (PMID 39540153, 2024). "PEComas typically display a myomelanocytic phenotype with expression of melanocytic markers, such as HMB-45, melan-A, and microphthalmia-associated transcription factor (MiTF), as well as myoid markers, such as smooth muscle actin (SMA) and caldesmon." (PMID 34301321, 2021). "Perivascular epithelioid cell tumor (PEComa) is a less common mesenchymal tumor, expressing melanocytic and myogenic markers such as actin, desmin, calponin, human melanin black (HMB) 45, melanA, and microphthalmia-associated transcription factor (MITF)." (PMID 27842558, 2016). "PEComas are distinguished by the expression of smooth muscle markers (e.g., SMA, h-caldesmon, desmin) and melanocytic markers (e.g., HMB-45, melan-A, MITF)." (PMID 40002892, 2025). "Immunohistochemically, PEComas are positive for both smooth muscle markers (e.g., SMA, h-caldesmon, desmin) and melanocytic markers (e.g., HMB45, melan-A, tyrosinase, MITF)." (PMID 40002892, 2025). "PEComas are characterized by the immunoexpression, among others, of both melanocytic markers (HMB-45, Melan-A, MiTF, and PNL2) and myoid markers (desmin, smooth muscle actin, muscle-specific actin, myosin, and calponin)." (PMID 40647483, 2025). "Since PEComas are almost always immunoreactive for smooth muscle (actin, desmin, caldesmon) markers, as well as melanocytic (HMB-45, melan-A, MiTF) markers, this characteristic immunohistochemical profile provides accurate diagnosis." (PMID 34442003, 2021). "Since PEComas are nearly always immunoreactive for both melanocytic (HMB-45, melan-A, MiTF) and smooth muscle (actin, desmin, caldesmon) markers, characteristic histologic and immunohistochemical findings provide the most accurate means of diagnosis." (PMID 28270196, 2017). "In summary, we report 2 cases of PEComas-NOS arising in the GI tract, one of which was confirmed to harbor a PSF-TFE3 gene fusion and to exhibit upregulation of MiTF and its downstream genes." (PMID 25621681, 2015). "PEComas are immunoreactive for both smooth muscle (desmin, SMA, muscle-specific-actin, muscle myosin, and calponin) and melanocytic (HMB-45, Melan-A/MART-1, tyrosinase, and MITF) markers." (PMID 39759135, 2024). "Overexpression of TFE3, member of the microphthalmia transcription factors family (MiTF), mediates the expression of cathepsin-K, which might be another IHC marker helpful to diagnose TFE3-altered PEComas." (PMID 34680376, 2021). "TFE3 expression is also seen in alveolar soft part sarcoma, melanotic Xp11 TRCs, Xp11 RCC, and rare PEComas that are negative for MiTF." (PMID 24735727, 2014). "A significant subset of PEComas show overexpression of MITF in the absence of TFE3 expression." (PMID 39759135, 2024).
lung carcinoma (15 papers, 2008 to 2025). "Whether MITF regulates stemness and is associated with chemoresistance of lung cancer cells is an unanswered question." (PMID 33293474, 2020). "The fundamental function of PTGR1 in lung cancer progression is unclear but MITF-mediated inflammation involved in regulating PTGR1 has been proposed." (PMID 33293474, 2020). "In this study, we identified differential expression of MITF in our lung cancer metastasis cell model by expression microarrays." (PMID 33293474, 2020). "Our data suggest that MITF plays a suppressive role in lung cancer progression and serves as a prognostic marker of NSCLC." (PMID 33293474, 2020). "However, subsequent studies have suggested that MITF has multiple effects in cancers such as hepatocellular carcinoma, pancreatic cancer, lung cancer and papillary RCC." (PMID 34208068, 2021). "Similarly, studies have shown that MITF is involved in autophagy and cellular homeostasis in lung cancer." (PMID 34208068, 2021). "Since FZD7 is a transmembrane receptor in the WNT pathway, we further investigated whether MITF regulated cell invasion through FZD7 in lung cancer cells." (PMID 33293474, 2020). "Our data suggested that MITF was an independent prognostic marker for NSCLC and might have a suppressive role in lung cancer progression." (PMID 33293474, 2020). "Indeed, we observed that the correlation between MITF and CRYAB is also present in colorectal cancer, but not in breast nor lung cancer (data available in CANCERTOOL40)." (PMID 30310055, 2018).
osteopetrosis (15 papers, 2010 to 2024). Osteopetrosis, also known as marble bone disease, is a descriptive term that refers to a group of rare, heritable disorders of the skeleton characterized by increased bone density on radiographs. "Another gene associated with osteopetrosis is MITF(microphthalmic-associated growth factor), which encodesa transcription factor that acts downstream of the RANK/RANKL pathway." (PMID 37465191, 2023). "MITF is a pleiotropic transcription factor as MITF-mutant mice displayed a number of phenotypic defects such as retinal degeneration, hearing loss, osteopetrosis and abnormal pigmentation." (PMID 35387064, 2021). "Accordingly, M-CSF, PU.1, MITF, and Bcl-2 mutation lead to osteopetrosis in mice resulting from reduced OC progenitor cells." (PMID 30700695, 2019). "Another mutated gene associated with osteopetrosis is MITF (microphtalmia-associated growth factor) that encodes for a transcription factor acting downstream RANK/RANKL pathway." (PMID 30837952, 2019). "Furthermore, biallelic MITF mutant alleles are associated with COMMAD syndrome characterized by coloboma, osteopetrosis, microphthalmia, macrocephaly, albinism, and deafness." (PMID 35665902, 2022). "Redundancy between MITF and TFE3 was also suggested by the observation that loss of function mutation in either gene leads to normal bone development whereas simultaneous knockout of both factors resulted in the development of severe osteopetrosis in mice." (PMID 32881934, 2020). "Besides, MITF was identified to promote macrophage survival and MITFmi/mi mice exhibited severe osteopetrosis." (PMID 28607030, 2017). "Extremely rare forms of osteoclast-rich osteopetrosis are caused by defects in the carbonic anhydrase 2 (CA2), pleckstrin homology and RUN domain-containing M1 (PLEKHM1), leucine-rich repeat kinase 1 (LRRK1) and melanocyte-inducing transcription factor (MITF) genes." (PMID 33970241, 2021). "The MiTF/TFE3 redundancy establishes a critical role for the MiT family in osteoclastogenesis and provides an interpretation of why osteopetrosis in humans has not been related to MiTF genetic alterations." (PMID 33441180, 2021).
uveal melanoma (15 papers, 2012 to 2025). A melanoma derived from melanocytes of the uveal tract. "Given that cutaneous and uveal melanoma are governed by mutations in different genes and are found in different environments, the role of MITF might differ between skin and eye melanomas, although we see many similarities." (PMID 35682684, 2022). "This rare melanoma of the eye is dependent on the cooperation between the SWI/SNF complex and the melanocyte-inducing transcription factor (MITF) to drive a transcriptional program essential for uveal melanoma cell survival." (PMID 38390898, 2024). "We explored the role of MITF in Uveal Melanoma (UM) using a cohort of 64 patients enucleated at the Leiden University Medical Center." (PMID 37240204, 2023). "Aligned with that, the HDAC trichostatin A (TSA) increases miR-137, which in turn reduces MITF expression in uveal melanoma cells." (PMID 35682684, 2022). "In contrast to skin melanoma tumors, where SAMMSON is invariably co-amplified with Melanocyte Inducing Transcription Factor (MITF) on chromosome 3, uveal melanoma cells are characterized by frequent (50−60%) loss of an entire copy of chromosome 3." (PMID 34508176, 2022). "Yan and coworkers found similar effects in uveal melanoma cells, where they identified MITF, BCL2 and cyclin D2 as potential targets of miR-182." (PMID 24575749, 2014). "Since c-Met is a direct target of MITF, we also investigated the effect of c-Met on uveal melanoma cells." (PMID 22848417, 2012). "In addition, miR-137 has been found to suppress uveal melanoma cell growth by targeting MITF and CDK6." (PMID 22419847, 2012). "Positive expression of MITF, however, remains in most adult clinical uveal melanoma specimens." (PMID 22848417, 2012). "MiR-137 acts as a tumor suppressor in uveal melanoma cell proliferation through downregulation of its targets MITF and CDK6; miR-34a acts as a tumor suppressor in uveal melanoma cell proliferation and migration through downregulation of c-Met." (PMID 23441115, 2013). "The treatment of uveal melanoma cells with the agonist LNS8801 also induced the expression of melanin and differentiation markers such as MITF, which directs transcription of melanocyte specific genes required for melanin synthesis, and the downstream effector TYR." (PMID 37035582, 2023). "Importantly, analyses of TCGA data confirmed that high expression of PAX3, SOX10, MITF and TFAP2A are defining features of uveal melanoma patient samples and such TFs have been validated as selective cancer dependencies in UM cell lines by large-scale functional genomics screens." (PMID 37400441, 2023).
Waardenburg syndrome type 2A (14 papers, 2018 to 2024). Waardenburg syndrome Type 2 caused by mutations in the MITF gene. "In humans, MITF mutations have been linked to the rare dominant pigmentation disorders Waardenburg Syndrome type 2A (WS2A) and Tietz Syndrome (TS) as well as the more serious COMMAD syndrome in compound heterozygotes." (PMID 32881934, 2020).
pancreatic cancer (12 papers, 2016 to 2025). "We therefore investigated the expression of MITF, TFE3, and TFEB by immunohistochemistry (IHC) across pancreatic tumor types." (PMID 41310888, 2025). "As observed in these figures, the lack of PP2A activity in pancreatic cancer cells clearly resulted in a reduction of nuclear MITF and TFE3, while significantly increased cytoplasmic retention of both proteins." (PMID 37996408, 2023). "Interestingly, and in agreement with the effects of HMT on PP2A methylation and activity, this treatment clearly reduced nuclear accumulation of MITF and TFE3 in pancreatic cancer cells." (PMID 37996408, 2023). "This is consistent with our finding that MITF and TFE3, upstream transcription factors of lysosome-related genes, are overexpressed in SPN, but not in four other pancreatic tumor types (PDAC, PanNET, ACC, and PBL) or benign pancreatic tissues." (PMID 41310888, 2025).
skin cancer (12 papers, 2015 to 2026). "For example, MITF dependency has stronger association with skin cancer (SuperDendrix weight = −0.69) than with BRAF(A) (SuperDendrix weight = −0.37)." (PMID 35382456, 2022). "As expected, COSMIC signature 7, predominantly found in UV exposure-linked skin cancers, predicted dependency on module #20 (BRAF/MAPK1/MITF/SOX10) for cell survival." (PMID 37460547, 2023). "By controlling pigmentation genes (e.g., TYR, TYRP1, and TYRP2), MITF is the main modulator of melanogenesis in response to environmental stimuli and was also proposed to exert an oncogenic role in several skin cancers." (PMID 32438927, 2020). "We infer that the expression of MiTF and p38 is higher in canine skin tumors and that this expression may be related to reduced aggressiveness of these neoplasias and less tumor progression." (PMID 41604042, 2026). "DepMap data from the online open-access “cancer dependency map,” which systematically identifies the genetic dependency of hundreds of cell lines, also showed that skin cancer was sensitive to GREB1 and MITF genetic perturbations." (PMID 37658191, 2023). "However, our data regarding the regulatory effect of MITF-M in DW-F5-induced cytotoxicity in multiple skin cancer cell lines indicate that the complete abolition of MITF expression, but not the blockage of Brn-2 expression, is the crucial factor for DW- F5-induced cell death." (PMID 26061820, 2015).
colon cancer (10 papers, 2014 to 2022). "After transfection of the HINT1 WT or 2KR construct into the A375 colon cancer cell line, the association of HINT1 with MITF and the endogenous expression levels of MITF target genes, including tyrosinase and CDK2, were investigated." (PMID 32636443, 2020).